ASXL1 (ASXL transcriptional regulator 1)
Diseases named in the same sentence as ASXL1 in open-access papers (continued):
Sharing a sentence is not in itself a finding about the gene and the disease.
myeloproliferative neoplasm (38 papers, 2012 to 2026). A clonal hematopoietic stem cell disorder, characterized by proliferation in the bone marrow of one or more of the myeloid (i.e., granulocytic, erythroid, megakaryocytic, and mast cell) lineages. "In EZH2-mutated patients with myelodysplastic or myeloproliferative neoplasms, the most common co-mutations were in ASXL1 (100%), NRAS, RUNX1, and STAG2 (29% each)." (PMID 33845873, 2021). "We aimed to determine the genotype distribution, allele frequency, and prognostic impact of IDH1/2, TET2, and ASXL1 single nucleotide polymorphisms (SNPs) in myeloproliferative neoplasms (MPNs)." (PMID 28218607, 2017). "This first-reported case of SF3B1-mutated myelodysplastic/myeloproliferative neoplasm with thrombocytosis (MDS/MPN-SF3B1-T), harboring coexisting ASXL1, JAK2 p.R683G, and CBL mutations challenges conventional genomic prognostic paradigms." (PMID 40772034, 2025). "The ASXL1 gene has been found altered in several malignant myeloid diseases such as myeloproliferative neoplasms, myelodysplastic syndromes, chronic myelomonocytic leukemia and de novo or secondary cases of acute myeloid leukemia." (PMID 36768643, 2023). "These NGS panels target genes that are associated with multiple hematological conditions, e.g., DNMT3A, TET2, ASXL1, and genes that are implicated in the pathogenesis of specific hematological disorders, e.g., JAK2 for myeloproliferative neoplasms (MPN)." (PMID 36290845, 2022). "Acquired somatic mutations in ASXL1 occur in approximately 10–20% of patients with MDS and 15–25% in myeloproliferative neoplasms (MPN) and AML." (PMID 31405121, 2019). "To determine whether the decreased ASXL1 expression is a direct cause of the functional alteration of the patient BMSCs, we next introduced WT ASXL1 into BMSCs derived from myeloproliferative neoplasms (MPN) patients." (PMID 29423272, 2018). "In another study, it was reported that mouse models of CH carrying mutations in Tet2, Dnmt3a, Asxl1, and Jak2 demonstrated that obesity accelerated the size of CH clones and increased the risk of developing a myeloproliferative neoplasm (MPN)-like phenotype, regardless of the specific mutation." (PMID 39119355, 2024). "The negative prognostic role of ASXL1 in acute and myeloproliferative disorders is now well recognized, and the assessment of this gene mutations in the clinical practice could help physician to design from the diagnosis a patient-tailored treatment." (PMID 29108298, 2017).
myelofibrosis (29 papers, 2012 to 2025). A partial or complete replacement of the bone marrow stroma by fibrous tissue. "In the newly developed myelofibrosis risk scores, the ASXL1 mutation is considered a high-risk category." (PMID 35145818, 2022). "ASXL1 mutations were identified in patients with PMF or post-ET/PV-myelofibrosis and associated with poor survival." (PMID 28218607, 2017). "This is the first report showing a clear association between the expansion of an ASXL1-mutated clone and the leukemic transformation of myelofibrosis." (PMID 24011025, 2013). "In almost all studies, and whatever the type of myeloid malignancy, ASXL1 mutations are associated with adverse features including, but not limited to myelodysplasia, myelofibrosis or progression to AML." (PMID 22436456, 2012). "In a study of MPNs based on the DIPSS-plus score (Dynamic International Prognostic Scoring System for primary myelofibrosis), ASXL1 mutation tended to be associated with an aggressive disease and a poor overall survival." (PMID 22436456, 2012). "In MPNs, for example, the proportion of ASXL1 mutations is higher in post-PV myelofibrosis (MF) and post-ET MF than in PV and ET." (PMID 22436456, 2012). "Given the role of LSD1 as an epigenetic regulator and its effect on ASXL1 clones, it is reasonable to further study whether the treatment effect is associated with other epigenetic regulator mutations observed in a subset of myelofibrosis in clinical settings." (PMID 38339265, 2024). "SRSF2, ASXL1 and U2AF1 mutations predict inferior survival in primary myelofibrosis, independently of other risk factors." (PMID 35740649, 2022). "It is particularly relevant in the context of pre-myelofibrosis to determine the impact of CALR/ASXL1 status on prognosis." (PMID 31244289, 2019). "We identified ASXL1 c.1934dupG in four cases of MPN (1 case of primary myelofibrosis and 3 cases diagnosed as ET with secondary fibrosis)." (PMID 30222780, 2018). "Mutations of ASXL1 and EZH2, for instance, have identified in myelofibrosis." (PMID 37760623, 2023). "ASXL1, EZH2, and SRSF2 mutations were associated with poor prognosis in primary myelofibrosis (PMF), and the patients could easily transform to s‐AML." (PMID 36799265, 2023). "Although the ASXL1 mutation's poor prognostic effect on myelofibrosis has been manifested, there are no studies about the impact of ASXL1 on oxidative stress in the literature." (PMID 35145818, 2022). "We demonstrated that JAK2V617F-positive PV patients harboring mutated ASXL1 exhibited poor myelofibrosis-free survival, and that mutated ASXL1 was present in 25% of post-PV myelofibrosis cases compared with only 4% of PV cases without myelofibrosis." (PMID 36068610, 2022). "While both JAK2V617F with WT Asxl1 and JAK2V617F;Asxl1+/− mice developed MPN (i.e., PV, ET, and MF), MPN occurred sooner in the latter with more progressing to myelofibrosis and secondary AML (sAML)." (PMID 36068610, 2022). "Certain mutations in epigenetic regulator genes have been documented in myelofibrosis, including TET2, ASXL1, EZH2, DNMT3A, and IDH1/IDH2 (Singh)." (PMID 31244289, 2019). "In a study focusing on early myelofibrosis (DIPSS low- or intermediate-1), baseline driver mutations did not affect the treatment response, but the presence of ASXL1 or SRSF2 had a deleterious impact." (PMID 38339265, 2024). "Considering the non-driver MPN somatic mutations in the CECs, ASXL1, TET2 and SRSF2 genes were among the most frequently shared mutations and are also known to be the most frequently mutated genes in Myelofibrosis." (PMID 34685741, 2021).
myelofibrosis (continued). "The multivariate analysis of all parameters under study clearly showed that the presence of so-called high risk mutations in ASXL1, EZH2, IDH1/2, or SRSF2 is not able to predict progression to myelofibrosis (p = 0.99)." (PMID 33541399, 2021). "Only two cases (n11 and n14), with a diagnosis of MPN (Myelofibrosis post Essential Thrombocytemia) and AML, had a single mutation in ASXL1, without mutations in the other genes tested." (PMID 30222780, 2018). "Conversely, the Myelofibrosis Transplant Scoring System (MTSS), established to aid in selecting patients for HSCT, considers only the non-CALR/MPL driver mutation genotype and ASXL1 mutation as risk factors." (PMID 38339265, 2024).
Myelodysplasia (24 papers, 2012 to 2025). Clonal hematopoietic stem cell disorders characterized by dysplasia (ineffective production) in one or more hematopoietic cell lineages, leading to anemia and cytopenia. "In addition, a second molecular context was evident: CSF3Rmut patients frequently harbored mutations typical of AML with myelodysplasia‐related changes, such as those in ASXL1 and SRSF2." (PMID 41423432, 2025). "The co-occurrence of two different myelodysplasia-associated somatic variants (CUX1/ETV6 and ASXL1/BCOR) was observed in 2 patients." (PMID 41188636, 2025). "The presence of mutations in at least one gene associated with myelodysplasia (i.e., SRSF2, SF3B1, U2AF1, ZRSR2, ASXL1, EZH2, BCOR, or STAG2) was significantly more frequent in older patients." (PMID 35805006, 2022). "FLT3-ITD, NPM1, and IDH1/2 were the most mutated genes, while also high proportion of ASXL1 and RUNX1 mutations could be detected, indicating the high proportion of myelodysplasia-related AML." (PMID 39453477, 2025). "Additionally, recent data demonstrated that myeloid specific mutations including TET2, ASXL1, and DNMT3A can induce inflammasome activation in myelodysplasia and exacerbate inflammation." (PMID 33648567, 2021). "Moreover, no patient with myelodysplasia‐related cytogenetic abnormalities presented mutations (0 of 19 in ASXL1+ vs 25 of 40, 63% in ASXL1−, P < .001)." (PMID 32216059, 2020). "In particular, the adverse-risk group has been expanded to include seven additional mutations: BCOR, EZH2, SF3B1, SRSF2, STAG2, U2AF1, and ZRSR2—together with ASXL1 and RUNX1 (already included in ELN 2017)—forming the “myelodysplasia-related” (MR) gene group." (PMID 41464583, 2025). "Eight myelodysplasia-associated somatic variants in the BCOR/BCORL1, DNMT3A, ASXL1, CUX1, and ETV6 genes were found in 7 patients (5 AA and 2 MDS-h patients, 17%); neither AA patient had evidence of myelodysplasia at the time of analysis." (PMID 41188636, 2025).
anemia (23 papers, 2010 to 2026). A reduction in the number of red blood cells, the amount of hemoglobin, and/or the volume of packed red blood cells. "In contrast, female sex, constitutional symptoms, anemia, peripheral blood blasts, and ASXL1 and SRSF2 mutations were correlated with inferior PFS." (PMID 36139644, 2022). "Related to these findings, we observed enhancement of age-associated phenotypes in hematopoiesis including anemia, myeloid-biased differentiation, hypocellular bone marrow, and expansion of surface marker-defined LT-HSCs in aged ASXL1-MT KI mice." (PMID 33758188, 2021). "Similar to the phenotypes of aged Vav-Cre ASXL1-MT KI mice, expression of ASXL1-MT in this model also caused anemia, thrombocytosis, and myeloid-biased differentiation with age." (PMID 33758188, 2021). "Time-to-event Cox analysis confirmed LT prediction for IDH1 mutation (HR 4.3), circulating blasts ≥ 3% (HR 3.3), SRSF2 mutation (HR 3.0), age > 70 years (HR 2.1), ASXL1 mutation (HR 2.0) and presence of moderate or severe anemia (HR 1.9)." (PMID 30683837, 2019). "Our results show that Asxl1-deficient mice exhibited anemia with impaired erythroid commitment and terminal erythroid maturation." (PMID 27352931, 2016). "Collectively, these data indicate that Asxl1 loss-mediated anemia is a consequence of the combinatorial effects of impaired erythroid maturation and increased apoptosis." (PMID 27352931, 2016). "In model I, we observed that ASXL1 and anemia were associated with poorer outcomes in PFS." (PMID 36139644, 2022). "However, when patients have both the predictive factors of poor response, namely, higher levels of EPO and ASXL1 mutations, alternative therapies would be recommended as the first-line therapy for anemia." (PMID 35821550, 2022). "A parallel time-to-event Cox analysis confirmed inferior LFS in patients with IDH1 mutation (HR 4.3), SRSF2 mutation (HR 3.0), ASXL1 mutation (HR 2.0), circulating blasts ≥ 3% (HR 3.3), age > 70 years (HR 2.1), and presence of sex-adjusted moderate or severe anemia (HR 1.9)." (PMID 30683837, 2019). "Bidirectional Effects on Erythropoiesis: While ASXL1 truncations repress erythroid differentiation via GATA1/KLF1 silencing (contributing to anemia), concomitant H3K27me3 loss at proliferative loci (e.g., HOXA9) may paradoxically expand early erythroid progenitors." (PMID 40772034, 2025). "Hematopoietic-specific deletion of Asxl1 using either Mx1-Cre or Vav-Cre resulted in MDS with progressive anemia and leukopenia compared with littermate controls." (PMID 35756660, 2022). "On a side note, HSCT therapy is highly recommended for patients with poor prognostic factors, e.g., significant anemia, a high burden of blasts, and mutations associated with increased mortality, such as SETBP1 and ASXL1." (PMID 35949766, 2022). "Conditional Asxl1 mutant (mimicking ASXL1 E635RfsX15) knock-in mice develop anemia, erythroid dysplasia, thrombocytosis, clonal hematopoiesis with age, and acute leukemia with the introduction of additional mutations." (PMID 36068610, 2022). "It appears that ASXL1-MT promotes age-related changes in the hematopoietic system of Vav-Cre ASXL1-MT KI mice (e.g. anemia, myeloid-skewed differentiation, and hypocellular bone marrow)." (PMID 33758188, 2021). "In mouse model experiments, ASXL1 silencing together with oncogenic NRasG12D generates hepatosplenomegaly and progressive anemia, emphasizing ASXL1’s function in myeloid malignancies." (PMID 34627254, 2021). "In addition to lymphocytosis, anemia, and thrombocytopenia were also identified in Asxl1−/−Ezh2−/− CLL mice." (PMID 40561338, 2025). "On the other hand, we have previously reported superior spleen and anemia response in the absence of ASXL1 mutations in momelotinib treated patients with MF." (PMID 36599841, 2023). "Among 65 patients that who did not have thrombocytopenia, anemia, peripheral blasts, and ASXL1 mutations, most of the patients were diagnosed with pre-PMF (30/65, 46.1%)." (PMID 36139644, 2022).
anemia (continued). "Analyses of peripheral blood cells showed mild leukocytopenia and mild anemia, which are prominent when compared with age-matched control mice, as well as moderate thrombocytosis in aged Vav-Cre ASXL1-MT KI mice (hereinafter, all experiments were performed with 20–24-month-old for aged mice)." (PMID 33758188, 2021). "Since ASXL1-MT appears to accelerate aging of LT-HSCs (e.g. anemia, myeloid-skewed differentiation, and hypocellular bone marrow), we compared alteration of gene expression profiles associated with physiological aging of LT-HSCs (GSE48893) with this RNA-seq analysis data." (PMID 33758188, 2021). "Logistic regression analysis identified IDH1, ASXL1 and SRSF2 mutations, very high-risk karyotype, age > 70 years, male sex, circulating blasts ≥ 3%, presence of moderate or severe anemia and constitutional symptoms, as predictors of LT in the first 5 years of diagnosis." (PMID 30683837, 2019). "Although defective erythroid maturation and anemia are associated with the prognosis of patients with MDS or MDS/MPN, the role of ASXL1 in erythropoiesis remains unclear." (PMID 27352931, 2016). "Mutations in ASXL1 and CBL were frequent in refractory anemia with excess of blasts." (PMID 20678218, 2010). "Owing to the residual ASXL1 mutation, dasatinib treatment did not improve anemia." (PMID 41148513, 2026). "Even in patients with higher levels of EPO, there may be a chance to recover from anemia by DA therapy if they do not possess ASXL1 mutations." (PMID 35821550, 2022). "They found that knockdown of Asxl1 in a mouse expressing the oncogene NrasG12D accelerated the expected MPD, resulting in more severe symptoms of anemia and organomegaly as well as decreased lifespan." (PMID 35756660, 2022). "There was no impact of other laboratory (anemia, thrombocytopenia, serum tryptase) or genetic markers (mutations in SRSF2, ASXL1 or RUNX1) on OS." (PMID 37012462, 2023). "Risk factors cited for post-PV MF include advanced age, leukocytosis, reticulin fibrosis, splenomegaly and JAK2V617F allele burden and for post-ET MF include advanced age, leukocytosis, anemia, reticulin fibrosis, absence of JAK2V617F, use of anagrelide and presence of ASXL1 mutation." (PMID 26565403, 2015). "Similarly, our group generated a conditional Asxl1-mutant (mimicking ASXL1 E635RfsX15) knock-in (Rosa 26 locus) mouse model and found that the old mice with the Asxl1-mutant showed myeloid skewing, thrombocytosis, and mild anemia, without developing MDS or AML." (PMID 40773119, 2025).
Bohring-Opitz syndrome (23 papers, 2012 to 2026). "Background/Objectives: ASXL1 is a chromatin-associated gene implicated in both hematologic malignancies and neurodevelopmental disorders, including Bohring-Opitz syndrome (BOS)." (PMID 41751615, 2026). "De novo protein-truncating mutations of ASXL1 cause a rare genetic disorder, Bohring-Opitz syndrome (BOS; OMIM #605039)." (PMID 37053013, 2023). "Bohring-Opitz syndrome is a severe congenital disorder associated with a de novo mutation in the additional sex combs-like 1 (ASXL1) gene, and it is characterized by symptoms that include developmental delay and musculoskeletal and neurological features." (PMID 35119035, 2022). "Here we describe an apparently novel syndrome, likely caused by de novo truncating mutations in ASXL3, which shares characteristics with Bohring-Opitz syndrome, a disease associated with de novo truncating mutations in ASXL1." (PMID 23383720, 2013). "The phenotype of the index patient was found to resemble the mildest cases of Bohring-Opitz syndrome that is caused by ASXL1 mutations." (PMID 23476833, 2013). "We have to add that the presence of an ASXL1 mutation is unlikely in the index case according to comparative analysis between Bohring-Opitz syndrome and 20q11.21 microdeletion phenotypes." (PMID 23476833, 2013). "De novo truncating mutations in the ASXL1 gene are linked to Bohring-Opitz syndrome, a developmental disorder characterized by microcephaly; however, the role of Asxl1 in brain development remains unclear." (PMID 40276524, 2025). "ASXL1 mutations in Bohring-Opitz syndrome and in hematologic malignancies." (PMID 37053013, 2023). "Given the role of ASXL1 in chromatin modification, we hypothesized that pathogenic ASXL1 variants underlying Bohring-Opitz syndrome (BOS) have a unique DNAm signature." (PMID 35361921, 2022). "Similarly, heterozygous germline truncation of ASXL1 is the underlying cause of Bohring-Opitz syndrome, and related but distinct neurodevelopmental anomalies are associated with heterozygous germline truncation of ASXL2." (PMID 29037253, 2017). "Although the disease mechanism is unknown, craniofacial defects identified in homozygous Asxl1 knockout mice suggest that mutations in Bohring-Opitz syndrome result in a mutant protein with dominant-negative activity." (PMID 22876197, 2012). "Indeed, ASXL1 heterozygous nonsense mutations were recently described to cause Bohring-Opitz syndrome, a developmental disorder characterized by mental retardation, impaired intrauterine growth, trigonocephaly and wrist and metacarpophalangeal joint abnormalities." (PMID 22876197, 2012). "Neurodevelopmental syndromes, including Bohring-Opitz syndrome (BOS), associated with mutations in ASXL1, present with diverse clinical manifestations." (PMID 40276524, 2025). "This study conducted direct qualitative and quantitative phenotyping in 15 individuals with Bohring-Opitz Syndrome (BOS- ASXL1) and Bainbridge-Ropers Syndrome (BRS- ASXL3)." (PMID 38027485, 2023). "Two specific CMDs discussed here include Bohring-Opitz Syndrome (BOS), caused by truncating variants in ASXL1, and Bainbridge-Ropers Syndrome (BRS), caused by truncating variants in ASXL3." (PMID 38027485, 2023). "Bohring-Opitz syndrome (BOS; [MIM# 605039]) is caused by autosomal dominant truncating variants in ASXL1 and was molecularly defined in 2011." (PMID 35361921, 2022). "Here, we investigated molecular mechanisms pertaining to NC-related symptoms in Bohring-Opitz syndrome (BOS), a developmental disorder linked to mutations in the Polycomb group factor Additional sex combs-like 1 (ASXL1)." (PMID 31006630, 2019). "As an exception, trigonocephaly in Bohring-Opitz syndrome reflects specific molecular properties of the chromatin modifier ASXL1 gene." (PMID 29093661, 2017).